IL2 (interleukin 2)
Diseases named in the same sentence as IL2 in open-access papers (continued):
Sharing a sentence is not in itself a finding about the gene and the disease.
gastric cancer (continued). "Lycopene treatment had significantly increased blood IL-2, IL-4, IL-10, TNF-α levels and reduced the IL-6 level in gastric cancer rats." (PMID 21686188, 2011). "In this study, blood IL-2, IL-4, IL-10 and TNF-α levels in gastric cancer model control rats were significantly lower than those in normal control rats." (PMID 21686188, 2011). "Compared with the normal control rats, blood IL-2, IL-4, IL-10 and TNF-α levels were significantly reduced in the gastric cancer model rats, while blood IL-6 level was significantly increased." (PMID 21686188, 2011). "This study shows that the immunotherapy with low-dose IL-2 plus the pineal hormone MLT is a new well tolerated and effective therapy of advanced tumours of the digestive tract, mainly in gastric cancer and hepatocarcinoma." (PMID 8512825, 1993). "In patients with gastric cancer at stage IV of the disease, multidirectional changes occur when studying proinflammatory cytokines: a decrease in TNF-α, IL-8, TNF-β, as well as an increase in IL-2, IFNγ, IL-17A, and IL-6." (PMID 40806737, 2025). "The roles that such cytokines, such as IL-2, TNF-α, and IFNs, could play would prove to be of significant importance in the suppression of gastric cancers." (PMID 40309351, 2025). "Combinations of checkpoint blockade with antibodies such as trastuzumab and cetuximab, or with long half-life IL-2, have been safely tested in patients with advanced HER2-positive gastric cancer, recurrent/metastatic head and neck cancer, and other advanced solid tumors." (PMID 34818534, 2021). "Applying a non-parametric statistical method (rank transformation) the IL-2 values significantly increased in the group of gastric cancer patients receiving mistletoe treatment." (PMID 23033982, 2012).
glioblastoma (48 papers, 2009 to 2025). The most malignant astrocytic tumor (WHO grade IV). "T98G glioblastoma cells were transfected with a plasmid encoding T-antigen and were treated with IL-2, Rantes, IFN-γ, IL-1β, IL-13 and MCP1 at 12, 24, and 36hrs post-transfection." (PMID 26061652, 2015). "We observed similar results for IL-2– and IL-7–expanded glioblastoma patient CD8+ T cells in terms of CD107aHi degranulation, IFN-γ, and tumor-necrosis factor-alpha (TNF-α) production." (PMID 40244705, 2025). "In line with this, purified NK cells cultured in NK MACS® medium with human AB serum and IL-2 demonstrated high cytotoxicity against primary glioblastoma stem cells." (PMID 38994999, 2024). "That is why IL-21, along with IL-2, IL-15 and mesothelin peptides, have been employed to evaluate humoral response using blood samples from patients with glioblastoma." (PMID 37759505, 2023). "In the work of Zhenjiang and colleagues, the peripheral blood of patients with glioblastoma was analyzed (glioblastoma = 145; non-glioblastoma = 60) to measure the circulating T cells in the absence or presence of serum cytokines such as IL-2/IL-15/IL-21." (PMID 37759505, 2023). "In the presence of IL-2, Vδ1 T cells predominate in patients with glioblastoma, with enhanced immunosuppressive function of Vδ1 T cells and reduced cytotoxicity of Vδ2 T cells." (PMID 37759912, 2023). "Blockade with a specific KIR2DL-1,2/3 mAb reversed NK-cell inhibition and significantly enhanced degranulation and IFN-γ production of IL-2-preactivated NK-cells in the presence of primary glioblastoma (GBM) cells." (PMID 36601109, 2022). "Infusion of HER2 CAR-T cells causes T cell proliferation and IFN- and IL-2 release in an orthotopic murine glioblastoma xenograft model, mediating the regression of HER2-positive glioblastoma." (PMID 35269652, 2022). "The use of exogenous IL-2 to enhance NK-cell activity has been evaluated in glioblastoma and other cancer patients but was limited by pronounced in vivo toxicity." (PMID 35474089, 2022). "In particular, utilizing NK cells activated with HSP70 and IL-2 is promising since these cells can cross the blood brain barrier and infiltrate to the site of glioblastoma." (PMID 33800301, 2021). "Nevertheless, while actively suppressed in glioblastoma tumors, even patient-derived autologous NK cells can recover their cytolytic activity upon ex vivo culture with IL-2 or IL-15, in particular directed to GB stem-like cells." (PMID 31798595, 2019). "The resulting IL-13Rα2-specific ε-TRuC-T cells lysed target-positive U251 glioblastoma cells at various effector-to-target ratios and caused release of IFN-γ and IL-2 by T cells." (PMID 31064990, 2019). "When Vγ9Vδ2 T cells, aminobisphosphonate, and IL-2 were delivered intratumorally in a murine xenotransplant model for glioblastoma, potent tumor reduction was observed." (PMID 29937769, 2018). "HddSBL reduced the tumor secreted serum rat IL-2 level upregulated by oncoVV, promoted viral replication, as well as inhibited the expression of antiviral factors in C6 glioblastoma cell line." (PMID 29701680, 2018). "Although several clinical trials by intratumoral injection of LAK cells combined with IL-2 for the glioblastoma patients have been carried out, most of their therapeutic effects have not shown a significant survival benefit." (PMID 25009822, 2014). "Both allogeneic and autologous IL-2 activated NK cells, furthermore, recognize and kill human glioblastoma cells with stem cell-like properties." (PMID 25009822, 2014). "Herein, we report that DC vaccination reproducibly enhances IL-2 responsiveness in PBL, and increases in overall survival were observed in glioblastoma patients whose IL-2 responsiveness was elevated." (PMID 24883189, 2014). "NK cells activated with IL-2 and IL-5 could recognize and destroy CSCs in glioblastoma, colon cancer, melanoma, and breast cancer." (PMID 40647402, 2025).
glioblastoma (continued). "Moreover, VPA-treated glioblastoma cells stimulated CAR-T cells to produce higher levels of inflammatory cytokines (IL-2, IFN-γ, and IL-6)." (PMID 39877353, 2024). "Experiments on human breast, colon, melanoma, and glioblastoma reveal that IL‐2 and/or IL‐15 activated NK‐cells could identify solid tumor CSCs by involving the receptor‐dependent mechanism, eventually leading to CSC‐elimination in these tumors." (PMID 37698048, 2023). "As IL-2 preactivation is critical for the cytolytic capacity of NK-cells in glioblastomas, we further evaluated whether tumor-infiltrating T-cells were able to produce IL-2 upon stimulation." (PMID 35474089, 2022). "As triggering of freshly isolated tumor-derived NK-cells in glioblastomas is substantially impaired, we also postulated that IL-2 signaling is required to upregulate activating receptors on tumor-derived NK-cells in glioblastomas as has been previously reported for other tumor entities." (PMID 35474089, 2022). "Instead, upregulation of activating molecules like NKG2D on NK cells or the use of allogeneic and autologous cytokine-activated (IL-2 or IL-15) NK cells are important to prime NK cells to eliminate glioblastoma cells and overcome the failure of immune surveillance." (PMID 33800301, 2021). "We could show that the adoptive transfer of ex vivo TKD/IL-2-activated mouse NK cells or the inhibition of PD-1 resulted in tumor growth delay and an improved overall survival (OS) in a syngeneic glioblastoma mouse model." (PMID 30967859, 2019). "Mice with membrane Hsp70 positive syngeneic GL261 glioblastoma or human xenograft A549 lung tumors were sham-treated with PBS or injected with ex vivo TKD/IL-2-activated mouse/human NK cells and mouse/human PD-1 antibody either as a single regimen or in combination." (PMID 30967859, 2019). "Therefore, reciprocal responses to IL-2 and IFN-γ after DC vaccination are also associated with one of the primary survival endpoints in glioblastoma." (PMID 24883189, 2014). "Immunotherapyusing proinflammatory cytokines such as IL-2 or IL-12 may prolongsurvival with glioblastoma." (PMID 20111737, 2009). "It has been reported that glioblastoma (GBM) CSCs are vulnerable to IL-2/IL-15-activated NK cells due to their expression of cytotoxicity receptors and ligands (i.e., PVR and Nectin-2) and the reduction of MHC-I molecules on their surface." (PMID 33530455, 2021). "The effects of a singular or combined treatment consisting of ex vivo TKD/IL-2-stimulated mouse effector cells (NK) and immune checkpoint inhibitor blockade against mouse PD-1 (PD-1) were determined in mice with membrane Hsp70 positive orthotopic glioblastomas (GL261)." (PMID 30967859, 2019). "The systemic administration of NK cells treated with IL-2 and HSP-70 crossed the blood-brain barrier and targeted glioblastoma cells in an induced glioblastoma multiforme (GBM) rat model." (PMID 40647402, 2025). "CAR[D]-T, CAR[E]-T and to some extent CAR[C]-T also showed potent cytotoxicity against glioblastoma cell lines expressing lower levels of IL13Rα2 and secreted IFN-γ in a dose-dependent manner and IL-2." (PMID 37563127, 2023). "Recombinant IL-2 (rIL-2) and human double-stranded DNA (dsDNA) increased 1.5-fold cytotoxic activity of patient IFN-DCs against autologous glioblastoma cells." (PMID 32326230, 2020). "We have previously shown that recombinant interleukin 2 (rIL-2) and human double-stranded DNA (dsDNA) enhanced the expression of mTNFα on IFN-DCs from glioblastoma patients." (PMID 32326230, 2020). "Patients with glioblastoma (GBM) are locally and systemically immunosuppressed as lymphocyte counts, mainly CD4+, are reduced and T-cell proliferation, in response to interleukin-2 (IL-2), is impaired." (PMID 28107450, 2017). "We demonstrated that these glioblastoma cells were put into relatively cytokine "rich" environment produced by AT-MSC containing IL-1β, IL-1ra, IL-2, IL-4, IL-6, IL-8, TNF-α, IFN-γ, CCL5, CCL26, CXCL10, PDGF-bb." (PMID 20509882, 2010).
glioblastoma (continued). "Currently, researchers are also exploring these problems above, about γδ T cell expansion although there is no mature method to address these issues, one study demonstrated that Vγ9Vδ2 T cells from glioblastoma (GBM) patients could be expanded using zoledronic acid and interleukin-2 (IL-2)." (PMID 40370457, 2025). "Additionally, since cytokine secretion by CAR-T cells targeting cancer cells indicates T cell activation and specific cytotoxicity, the levels of the classic cytokines (IFN-γ, IL-2, and TNF-α) were measured when CAR-T cells were incubated with glioblastoma cells to assess the cytokine profile." (PMID 39877353, 2024). "In our recent experiment on glioblastoma multiform (GBM), the anti‐tumor effect of HSP70/Il‐2‐treated NK‐cells was analyzed and confirmed through both in vitro study and in vivo rat GBM models." (PMID 37698048, 2023). "Moreover, in the serum of patients with glioblastoma (the most typical parenchymal brain tumor), it has been reported that there is a significant overexpression of IL-6, IL-1β, TNF-α, IL-10, VEGF, FGF-2, IL-8, IL-2, and GM-CSF." (PMID 37368708, 2023). "Indeed, this was likely to be TGF-β isoform 2, originally described as glioblastoma-derived T cell suppressor factor, given its discovery in GBM cell lines and patient serum, where it was noted to be immunosuppressive to T-cell proliferation through IL-2 dependent and independent pathways." (PMID 31973059, 2020). "EVs from patients suffering from glioblastoma (GBM) are capable to polarize CD14+ and CD163+ monocytes toward the M2 anti-inflammatory phenotype, enhancing blood serum concentrations of colony-stimulating factor 2 and 3, as well as to detect interleukin-2, -4, and -13." (PMID 37511010, 2023). "We detected significant cytotoxicity against glioblastoma cells and increased levels of IFN-γ, TNF-α, and IL-2 in the presence of anti-CAIX CAR-T cells but not in control T cells." (PMID 31935881, 2020).
inflammatory bowel disease (47 papers, 2010 to 2026). A spectrum of small and large bowel inflammatory diseases of unknown etiology. "In line with the reported inverse association between Se status and inflammatory bowel diseases, increasing the concentration of Se in the media generated a dose-dependent suppressive effect on IL2 production of sorted CD4 Teffs following TCR stimulation." (PMID 33851102, 2021). "Additionally, while IL-2-deficient mice develop progressive inflammatory bowel disease closely resembling human ulcerative colitis (UC), UC patients exhibit a significant reduction in the expression of IL-2." (PMID 33814980, 2021). "However, that concept of a TCGF changed with observation that a genetic deficiency of IL-2 or IL-2R resulted inflammatory bowel disease (IBD), an overactive immune system situation." (PMID 26529512, 2015). "This subset, characterized by IL-17 A, IL-2, TNF-α, and IFN-γ secretion, has been implicated in inflammatory diseases such as Crohn’s disease and inflammatory bowel disease." (PMID 41194200, 2025). "IL-2, IL-1β, IFN-γ, IL-6, TNF-α, and IL-8 is a pro-inflammatory cytokine associated with inflammatory bowel disease, and the pro-inflammatory cytokine response is a critical pathophysiological factor in the acceleration of the occurrence and development of UC." (PMID 39473926, 2024). "The pivotal involvement of IL-2 and IL-17 in the pathogenesis of inflammatory bowel disease highlights the potential for modulating their levels as a novel therapeutic approach." (PMID 38540888, 2024). "The previous study has shown that the disrupted IL-2 gene contributes to developing an inflammatory bowel disease similar to UC in humans and IL-2 and IL-4 were defined as anti-inflammatory cytokines which are negatively associated with the occurrence of UC." (PMID 37205093, 2023). "It has been studied that IL-2, IL-3 and IL-8 expressions (which play an important role in intestinal inflammation such as in inflammatory bowel disease [IBD]) are regulated by NF-κB during CD28 co-stimulation." (PMID 35909996, 2022). "Previously, increased levels of CD4+ T cells-derived IL-2 and IL-21 have been reported in inflammatory bowel disease." (PMID 31936604, 2020). "Based on these observations, in vivo expansion of Foxp3+ Tregs using IL-2 and other methods has been explored as a potential therapeutic for human inflammatory bowel disease (IBD)." (PMID 30930900, 2019). "In an in-vitro study, a significant reduction was seen in several inflammatory biomarkers including tumor TNF-α, IL-1α, IL-6, IL-8, T-cell interferon-gamma (IFN-γ), and IL-2, in the presence of ≥10 μg/ml garlic extract in inflammatory bowel disease." (PMID 30683061, 2019). "In this context, it should be notes that increased concentrations of IL-1β and IL-2 have been reported in endoscopic mucosal biopsy specimens from patients with inflammatory bowel disease." (PMID 23497090, 2013). "Not overexpression but Il2 knockout leads to a disrupted immune response and predisposition to inflammatory bowel disease." (PMID 39746095, 2025). "While increased immune responses were observed using IL-2 as an adjuvant, altered levels of IL-2 have been found in inflammatory bowel disease patients and the complex interaction IL-2 has between inducing tolerance versus inflammation may be problematic for its use as a mucosal adjuvant." (PMID 31623188, 2019). "Finally, using IL-2 as a proxy to identify and isolate this hyperactivated subpopulation, we establish downstream functional consequences for Th17 cell maintenance and transdifferentiation with important implications for Th17-driven inflammatory disorders such as inflammatory bowel disease and EAE." (PMID 40674215, 2025). "Sequestration of IL-2 by TFR is the most likely mechanism, and was elegantly described in Treg in a mouse model of inflammatory bowel disease." (PMID 36420277, 2022).
inflammatory bowel disease (continued). "It is well known that IL-6 is an important proinflammatory cytokine involved in the development of inflammatory bowel diseases (IBD), whereas considerable evidence suggest the important role played by IL-2 in maintaining a healthy immune response in the gut." (PMID 36432588, 2022). "Accumulating evidence supports the concept that an aberrant balance between Tregs and Teff contribute to the pathology of intestinal inflammation and that the IL-2/Treg axis is a potential pathway to exploit for the treatment of inflammatory bowel disease (IBD)." (PMID 30930900, 2019). "Moreover, a meaningful correlation was observed between proinflammatory cytokines such as TNF and IL-2 concentration in the poor prognosis of the disease among the patients with pre-existing gut-related health conditions such as inflammatory bowel disease (IBD)." (PMID 34066983, 2021).